AFP (alpha fetoprotein)
Diseases named in the same sentence as AFP in open-access papers (continued):
Sharing a sentence is not in itself a finding about the gene and the disease.
liver disease (continued). "Moreover, this study showed that the addition of PTX3 to AFP may allow further identification of HCC in the HBV-related liver diseases." (PMID 33219288, 2020). "Although serum AFP levels are efficient at predicting disease outcomes and monitoring tumor progression in AFP-producing HCC patients, the updated American Association for the Study of Liver Disease (AASLD) guidelines no longer recommend AFP testing as a part of diagnostic evaluation." (PMID 30176913, 2018). "Therefore, it should be determined whether HCC is present when a patient with liver disease exhibits serum AFP elevation, especially low-level elevation (AFP < 400 ng/ml)." (PMID 29228649, 2017). "Generally, PIVKA-II performed a better diagnostic effectiveness than AFP in differentiating HCC from non-HCC hepatic diseases and the AUROC for PIVKA-II could reach 0.8, which is obviously better than AFP (DeLong P = 0.001 and P < 0.001, respectively)." (PMID 28863782, 2017). "Additionally, the subjects in this study were in-patients; thus, the value of this method for identifying out-patients with HCC among liver diseases with elevated serum AFP levels is unknown." (PMID 29228649, 2017). "However, as this patient had no previous history of liver disease and did not exhibit abnormal liver function, it was unlikely to conclude that the AFP abnormality was associated with liver disease." (PMID 24959228, 2014). "Elevated AFP level is not always associated with liver disease." (PMID 22559879, 2012). "Differences in gender, BMI, diabetes mellitus, background of liver disease, tumor size, tumor number, MVI, BCLC staging, CNLC staging, AFP level, and surgical bleeding were statistically significant among the three groups (P<.05)." (PMID 40857604, 2025). "Median model for end-stage liver disease score is 10 (IQR:8–14), alpha-fetoprotein level 8 ng/mL (IQR:4–25), and tumor size 2 cm (IQR:1.1–3.0)." (PMID 40629061, 2025). "Liver disease may also be a possible nonmalignant cause of AFP elevation." (PMID 38672729, 2024). "Given the mixed findings in the literature regarding AFP and NAFLD, our study contributes to a more nuanced understanding of liver disease progression in specific patient populations, highlighting the importance of context in interpreting biomarker data." (PMID 39200880, 2024). "The study detailed the liver disease etiology, LI-RADS scores, characteristics and dimensions of HCC nodules, serum AFP concentrations, Edmondson–Steiner grading, and the expression of programmed cell death ligand 1 (PD-L1) in the tumor cells." (PMID 38791994, 2024). "In our context, the 80% cutoff offers the advantage of accurately reflecting true AFP changes attributable to HCC, while reducing the influence of varying liver disease conditions and inter-laboratory discrepancies." (PMID 38433845, 2024). "By inputting preoperative clinical factors such as tumor size and number, gender, age, AFP level, ALBI grade, and portal hypertension status, the online calculator can reveal RFS, RWM, and HSS at different time intervals for all three treatment options." (PMID 36016484, 2023). "The multivariate analysis showed that older age, male gender, higher AFP, higher ALBI grade, larger tumor diameter (3–5 cm vs. ≤3 cm), multinodularity, and the presence of portal hypertension were prognostic for RFS, RWM, and HSS." (PMID 36016484, 2023). "AFP ≥ 400 ng/mL is highly suggestive of HCC after excluding pregnancy, chronic or active liver disease, tumors of embryonic origin in the gonads, and tumors of the gastrointestinal tract, according to the HCC management guidelines." (PMID 36577952, 2022). "Patients were similar in gender, age, etiology of liver disease, MELD score, Child-Pugh score, and AFP." (PMID 35637985, 2022). "As to other indicators involved in liver disease (e.g., HDL, ALP, BUN) and tumor (AFP, CA199, CEA) diagnosis, minimal differences were observed among the indicated three groups." (PMID 35421921, 2022).
liver disease (continued). "ROC curve was used for joint diagnosis of hsa_circ_0006091 and AFP/RGS12, respectively in HCC s (n = 52) versus adjacent tissues s (n = 52), HCC versus benign liver disease tissues (n = 12)." (PMID 35068348, 2022). "An exploratory analysis was conducted to investigate the efficacy and safety of ramucirumab in advanced HCC patients with elevated AFP from REACH-2 and REACH by liver disease etiology." (PMID 34298750, 2021). "Predictors of cPR included younger age, specific liver disease diagnosis, lower MELD score, lower AFP (alpha-fetoprotein), lower neutrophil-to-lymphocyte ratio, radiographic Milan status at the time of transplant and lower number of LRT treatments." (PMID 33396289, 2020). "We screened possible prognostic factors for OS and PFS from 13 variables including gender, age, HBV DNA, CTP grade, portal hypertension (PHT), tumor size, TNM stage, AFP, BED10, APRI, NLR, PLR, and LMR." (PMID 33046985, 2020). "The GALAD scoring algorithm, comprising gender, age, AFP-L3, AFP, and DCP, has very good performance for HCC detection in large validation studies, including patients of diverse liver disease etiologies, even for detecting early stage HCC (BCLC 0/A)." (PMID 32793278, 2020). "Data collected included patient demographics, liver disease characteristics including CPT score, MELD-Na, AFP, type of imaging, tumor stage, and lab values at the time of HCC diagnosis." (PMID 30592722, 2018). "In conclusion, a combination of AFP and NLR showed better accuracy than either marker alone for differentiating HCC from liver disease." (PMID 30545306, 2018). "In conclusion, the combination of dual serum fluorescence, AFP, hepatic function tests and age is simple and valuable for identifying HCC in serum AFP-elevated liver diseases." (PMID 29228649, 2017). "The practical use of AFP is complex and suboptimal due to varying recommendations on the upper limit of normal (ULN) with associated variability in sensitivity and specificity depending on the ULN applied which may vary between aetiologies of the underlying liver disease, ethnicity and sex." (PMID 27308823, 2016). "To date, the use of AFP or other serological markers for non-invasive HCC diagnosis is not recommended by the European and American Society for the study of liver diseases." (PMID 26854169, 2015). "AFP and GGT are highly expressed in HPCs and are important in hepatocyte regeneration with impaired replication of mature hepatocytes in most liver diseases." (PMID 27335844, 2014). "For a patient with a history of liver disease, consensus for the diagnosis of HCC can be achieved with an elevated AFP level (≥200 ng/dL), along with a dynamic imaging study showing a hepatic tumor." (PMID 22808038, 2012). "The majority of control and cases had a viral etiology of their liver diseases, with HBV in 57 patients out of 96 controls and 71 out of 124 HCC cases, of which 29 were AFP-low HCC." (PMID 21092242, 2010). "Moreover, markedly raised serum alpha-fetoprotein (AFP) was detected besides elevated ALT, AST, TBIL, DBIL, and IBIL, indicating a cholestatic liver disease." (PMID 38819760, 2024). "The EASL and the American Association for the Study of Liver Diseases (AASLD) guidelines recommend an ultrasound examination every six months, with or without AFP, to screen for HCC." (PMID 37046471, 2023). "In the present study, we assessed the diagnostic accuracy of LC-SPIK, alone or in combination with standard serologic biomarkers (i.e., alpha-fetoprotein and protein induced by vitamin K absence or antagonist-II, PIVKA-II), for the detection of HCC among patients with dysmetabolic liver disease." (PMID 36005169, 2022). "Patients in the NLR ≥ 5 group tended to have a higher median AFP level (268 vs. 62, p = 0.02), incidence of PVT (51.9% vs. 32.9%, p = 0.02), more advanced liver disease, including a greater number of patients with CP score 6 (48.1% vs. 32%, p = 0.03) and ALBI grade 2 (67.9% vs. 39.9%, p < 0.001)." (PMID 36497316, 2022).
liver disease (continued). "Most patients had relatively stable AFP throughout follow-up, and no cases of cancer or liver disease developed during the follow-up." (PMID 35862314, 2022). "Multiple studies have achieved similar post-transplant recurrence rates with patients outside Milan when other variables have been met (low AFP, no vascular invasion, compensated liver disease, lack of undifferentiated histology)." (PMID 36290870, 2022). "During follow-up, there was no development of cancer or liver disease, and AFP levels were stable in most patients." (PMID 35862314, 2022). "We conclude that elevated AFP levels are a common, although non-specific, marker for NPC-associated liver disease." (PMID 35455589, 2022). "On the other hand, the specificity of AFP is far from satisfactory; elevated levels are frequently found in nontumor diseases of the liver." (PMID 35308139, 2022). "Furthermore, we compared the ROC curves of IgM-free AIM calculated from specificity and sensitivity with those of the conventional HCC biomarkers, AFP and DCP, for each liver disease related to NASH, HCV, HBV, and for all the patients." (PMID 34981443, 2022). "If liver lesions are found with elevated AFP levels in patients with no previous history of liver disease, the possibility of HAS should be considered." (PMID 34956891, 2021). "They found that both CircPanel and CircPanel+AFP showed a higher accuracy than AFP alone in distinguishing individuals with HBV-HCC from those with non-HCC liver disease." (PMID 34277444, 2021). "No other significant difference was found between groups with and without recurrence, including the etiology of liver disease and alpha-fetoprotein levels." (PMID 34287480, 2021). "It is the first reported study about site-specific PON1 glycosylation in AFP-negative liver disease conditions." (PMID 33889548, 2021). "For patients with AFP≥400 μg/L for more than 1 month, ≥200 μg/L for 2 months, or a gradually increased and stabilized AFP level but without pregnancy, gonadal embryoma, or active liver disease, HCC should be highly suspected." (PMID 34277397, 2021). "Current American Association for the Study of Liver Disease (AASLD) recommendations on surveillance of HCC are for ultrasound (US) imaging, with or without serum Alpha-fetoprotein (AFP) measurement for only the highest risk patients." (PMID 32374744, 2020). "Overall, 72 (86.7%) of all patients reviewed had at least one AFP measurement and 78 (93.9%) had at least one USS, of which 44 (56.4%) had at least one abnormal finding [diffuse increased echogenicity (53.8%) or evidence of portal hypertension (2.6%)]." (PMID 32381081, 2020). "Previous studies have confirmed that the serum AFP level decreased or increased in parallel with the serum ALT level in noncancerous liver diseases." (PMID 33490235, 2020). "By contrast, the specificity of the classical tumor marker AFP is considerably hampered by its association with non-GCT related conditions, such as liver diseases." (PMID 32363003, 2020). "Among that, for example, serum AFP level can be high in some non-cancerous liver disease while sometimes remains at a low level in definite HCC patients." (PMID 32697317, 2020). "The AUC for differentiating HCC from non-malignant liver disease was similar for AFP alone (Model 1: 0.88, 95% CI 0.84–0.93) and PIVKA-II alone (Model 2: 0.87, 95% CI 0.82–0.90)." (PMID 30675135, 2019). "Several studies have shown that PIVKA-II has a higher sensitivity and specificity than AFP for detecting HCC versus non-malignant liver diseases." (PMID 30675135, 2019). "In the next study by Mora’s group, 50 GCT patients with an increase of >20% in the AFP level during chemotherapy or follow-up, were investigated to determine whether elevated AFP indicated GCT progression or a hepatic disease." (PMID 31652641, 2019). "On the other hand, non-HCC samples (normal samples and liver disease samples) had significantly lower fucosylated AFP levels." (PMID 31451706, 2019).
liver disease (continued). "In 3,158 patients from 5 independent sites, this algorithm, referred to as the “Doylestown” algorithm, increased the AUROC of AFP 4% to 12% and had equal benefit regardless of tumor size or the etiology of liver disease." (PMID 30169533, 2018). "In our study, all the control samples consisted of sera collected from individuals without liver disease and with normal AFP levels." (PMID 27495068, 2016). "AFP values ≥ 400 ng/mL, macrovascular invasion, and portal hypertension were identified as significantly negative prognostic parameters in multivariate analysis for both treatment modalities." (PMID 25642245, 2015). "Although AFP-mRNA is frequently detected in the blood of patients with benign liver diseases or of HCC patients without extrahepatic metastases, it seemed to identify more aggressive tumors in terms of clinical behaviors." (PMID 24281095, 2010). "AFP can, however, be produced in many circumstances, including in relation to other liver diseases and is not present in all those with HCC." (PMID 20811639, 2010). "Other HCC patients had a non-viral etiology (non B, non C) of their liver diseases, with 20 AFP-low and 3 AFP-high HCC patients." (PMID 21092242, 2010). "For example, alpha‐fetoprotein (AFP), a commonly used biomarker for HCC, may not be elevated in some patients with HCC and can yield false‐positive results in certain benign liver diseases, thereby compromising diagnostic reliability." (PMID 41381803, 2025). "Exceptions may be those rare patients with hypogonadism, liver disease, and hereditary AFP elevation, who have an elevated hCGβ or AFP value without TGCT, which may be considered false positives." (PMID 40723290, 2025). "Regarding cost-effectiveness, the HCC-Check index incorporates markers (CK-1, EMA) that may not be part of routine liver disease panels, potentially increasing upfront laboratory costs compared to AFP testing alone." (PMID 40537682, 2025). "Further, serum AFP levels can be elevated in nonmalignant liver diseases, such as acute hepatitis." (PMID 38928187, 2024). "Adult livers lose the ability to produce AFP but damage to hepatocytes during chronic liver injury such as CCl4-induced HCC results in conferring the ability to produce AFP on regenerated and necrotized hepatocytes; therefore, AFP elevates in liver disease including HCC." (PMID 38204757, 2024). "In inactive CHB, normal AFP levels may indicate a less aggressive disease state, allowing for the development of NAFLD without the concurrent increase in AFP typically seen in more active or advanced liver disease." (PMID 39200880, 2024). "In a retrospective study aimed at determining the evolution of liver disease and its relationship with age and neurological impairment in A-T patients, a significant and direct correlation was found between the Klockgether Ataxia Scale (KAS) score and age, and levels of AFP, GGT, and ALT." (PMID 37147676, 2023). "The utility of AFP, AFP-L3, and DCP in LT for HCC has not been established, and recommendations for their application in HCC management are absent in the 2018 guidelines of the American Association for the Study of Liver Diseases." (PMID 34638251, 2021). "The following patient’s clinical characteristics were registered: age, gender, etiology of liver disease, liver function parameters (INR, total bilirubin level, serum creatinine, serum albumin), MELD score, Child Pugh class, the presence of ascites, and baseline AFP level (ng/mL)." (PMID 32793278, 2020). "However, data was scarce about what factors lead to an abnormal increase in AFP levels in patients with liver disease without developing HCC." (PMID 33490235, 2020). "Several risk factors reported to be associated with HCC recurrence, such as proportion of underlying liver disease, above Milan criteria, differentiation of HCC, vascular invasion, and preoperative alpha-fetoprotein level were not different between the two groups." (PMID 30728421, 2019).
liver disease (continued). "We have shown in the cross-sectional study that serum MDK could have a diagnostic role in AFP-negative HCC and may differentiate NASH-HCC from non-malignant liver disease." (PMID 27219517, 2016). "We performed a step-wise multiple linear regression analysis to determine whether ΔLDL-C was associated with age, gender, IFN-free regimen, clinical condition of liver disease, HCV-RNA, HCV core antigen level, BMI, AST, ALT, γ-GTP, platelet count, AFP, TC, LDL-C, TG, ΔHCV core antigen or ΔHCV-RNA." (PMID 27680885, 2016). "For hepatic pseudolesion complicated by primary non-viral (B, C, or G) hepatitis and abnormal AFP, regardless of whether the hepatic lesion can be biopsied, liver biopsy without contraindications is recommended to further characterize the hepatic disease." (PMID 24059753, 2013). "AFP has multiple limitations when applied to the detection of small tumors, and varies significantly in the presence of benign nodules or nonmalignant liver disease." (PMID 22760167, 2012). "Moreover, AFP levels remain normal in 15–30% of patients with advanced stage disease and increase in some patients with chronic hepatitis, liver cirrhosis, and other liver diseases, leading to high negative and false-positive rates." (PMID 30545306, 2018). "However, in this study, neither AFP was able to distinguish HCC from non-cancerous liver diseases, nor hTERTmRNA was correlated with AFP level (P = 0.201), suggesting that quantitative analysis of serum hTERTmRNA was much more sensitive for HCC diagnosis even in the early stage." (PMID 20482774, 2010). "Furthermore, periodic screening with alpha-fetoprotein and ultrasound has been recommended to promote early detection of HCC among selected populations with evidence of liver disease, but whether this policy results in a reduction in mortality rates has not been evaluated." (PMID 18558024, 2008). "This index integrates serum levels of cytokeratin-1 (CK-1), epithelial membrane antigen (EMA), albumin, and alpha-fetoprotein (AFP) into a formula designed to maximize discrimination between HCC and non-malignant liver disease." (PMID 40537682, 2025). "The levels of sGP73 and serum alpha-fetoprotein (sAFP) were measured in 134 HCC patients, 200 healthy controls (HCs), and 45 non-HCC patients with various liver diseases." (PMID 40297156, 2025). "Compared to AFP, DCP levels showed greater sensitivity and specificity in distinguishing HCC from chronic nonmalignant hepatic diseases." (PMID 37509493, 2023). "Firstly, we analyzed the proportions of abnormal AFP levels between AST ≤ 1× ULN and AST > 1× ULN in patients with different liver diseases in non-antiviral and antiviral groups." (PMID 36016291, 2022). "Current guidelines recommend the screening of HCC in at-risk patients using ultrasonography (US) of the liver every 6 months with or without serum alpha-fetoprotein (AFP), the most commonly used biomarker for liver disease detection." (PMID 33801181, 2021). "Whilst AFP is not recommended as a screening tool for HCC, it is often utilised in the monitoring of patients with liver disease." (PMID 32374744, 2020). "The use of a biomarker panel of AFP and PIVKA-II in combination with age and gender improved accuracy of detecting HCC and differentiating HCC from non-malignant liver disease in a US study population as compared to the individual biomarkers alone." (PMID 30675135, 2019). "In both cohorts, AFP and PIVKA-II concentrations were higher in patients with HCC compared to healthy controls and patients with non-malignant liver disease." (PMID 30675135, 2019). "UTS In and UTS Out patients did not significantly differ with regard to gender, age, liver diseases, Child classification, MELD score, AFP level, TACE and PET status." (PMID 29074969, 2017). "Patients: HCC vs. (liver disease without HCC and healthy)Tests: serum GOLPH2 levels by ELISA, AFP not measured.Outcomes: sensitivity, specificity and cut off value were available, but AFP levels were not tested." (PMID 22244200, 2012).